HSP90AA1 (heat shock protein 90 alpha family class A member 1)
Diseases named in the same sentence as HSP90AA1 in open-access papers (continued):
Sharing a sentence is not in itself a finding about the gene and the disease.
breast cancer (continued). "Finally, Because Wei’s reported the uncertainty of the diagnosis of plasma Hsp90AA1 and the heterogeneity of the HSP90AA1 protein secreted by tumor cells, we randomly screened the plasma of 32 ELISA-negative breast cancer patients." (PMID 34109171, 2021). "Notably, PCC-CM displayed a significantly higher expression of HSP90AA1, a stress-inducible isoform of heat shock protein that has been shown to correlate with unfavorable prognosis of breast cancer patients." (PMID 31963309, 2020). "Taken together, Hsp90AA1 promoted the proliferation of breast cancer cells, whilst BJ-B11 could be used to treat breast cancer." (PMID 31921692, 2019). "HSP90AA1 is a NANOG transcriptional target that contributes to the maintenance of cancer cell stemness, and its overexpression of HSP90AA1 was associated with unfavorable prognosis in breast cancer, while the inhibition of HSP90 reduces tumor stemness and promotes antitumor immunity." (PMID 33204396, 2020). "Similar to our research findings, a previous study has indicated that HSP90AA1 interacts with NME1 and increases NME1 lifetime by impeding its ubiquitin-proteasome-mediated degradation and suppresses breast cancer metastasis." (PMID 41507145, 2026). "Moreover, while the differential expression of HSP90AA1 and TAGLN2 was closely linked to fibroblast differentiation, the precise molecular mechanisms underlying these changes, particularly in the context of different breast cancer subtypes, remain unclear." (PMID 40299459, 2025). "The sub-localization of HSP90AA1 and HSP90AB1 in human cells certified that HSP90AA1 and HSP90AB1 proteins resided in the cytosol based on the evidence provided by 62 types of breast cancer cell lines, including MCF-7 and MDA-MB-231." (PMID 40076902, 2025). "In preclinical models of HER2-positive and trastuzumab-resistant breast cancer, HSP90 inhibitors, including NVP-AUY922 and a carbamate derivative, have demonstrated significant efficacy by inhibiting HSP90AA1." (PMID 40004024, 2025). "In this study, the core components regulate five key targets: MAPK1, LCK, JAK2, HSP90AA1, and EGFR, all of which are uniquely expressed in breast cancer." (PMID 39867914, 2024). "The high expression of HSP90AA1 and ATG5 in breast cancer patients predicts poor prognosis and poor clinical outcome of tumor patients." (PMID 38263419, 2024). "hsa-miR-27b-3p directly targets HSP90AA1 and Fzd7 in NSCLC, ROR1 in gastric cancer, and CBLB/GRB2 in breast cancer to suppresses cell proliferation, migration, invasion, and expression of MET." (PMID 34603447, 2021). "In this study, we investigated the expression patterns and prognostic values of different HSP90 family members (HSP90AA1, HSP90AA2, HSP90AB1, HSP90B1, and TRAP1) in breast cancer." (PMID 34109171, 2021). "Multiple heat shock proteins, including Hsp90AA1, Hsp90AB1, TRAP1, HspA5, HspB1, HspE1, HspD1, HspA1B, HspA8, HspA9, and HspA4, were significantly upregulated in breast cancer tissue." (PMID 31921692, 2019). "Hsp90AA1, Hsp90AB1, TRAP1, HspA5, HspB1, HspE1, HspD1, HspA1B, HspA8, HspA9, and HspA4 were validated as potential biomarkers for breast cancer tissue." (PMID 31921692, 2019). "Heat shock proteins showed the most significant change of all the upregulated domains, with Hsp90AA1, Hsp90AB1, TRAP1, HspA5, HspB1, HspE1, HspD1, HspA1B, HspA8, HspA9, and HspA4 identified in breast cancer tissue." (PMID 31921692, 2019). "Module 3 (4 genes) included regulation of cellular response to stress (BRCA1, CTNNB1, HSP90AA1, and WNT1) and breast cancer (BRCA1, CTNNB1, and WNT1)." (PMID 31608105, 2019). "Conversely, Hsp90AA1 overexpression upregulated vimentin and downregulated E-cadherin and occludin, suggesting that Hsp90 plays a vital role in EMT in breast cancer." (PMID 31921692, 2019).
breast cancer (continued). "The breast cancer subnetwork is found to contain (i) valid biomarkers including PIK3CA, PTEN, BRCA1, AR and EGFR; (ii) validated drug targets TOP2A, CDK4, HDAC1, IL6, BRCA1, HSP90AA1 and AR; (iii) synergistic drug targets EGFR and BIRC5." (PMID 35053185, 2021). "Interestingly, patients overexpressing two identified HSPs – HSPA2 and DNAJC20 exhibited longer survival, whereas overexpression of other four HSPs – HSP90AA1, CCT1, CCT2, CCT6A resulted in unfavorable prognosis for breast cancer patients." (PMID 31101846, 2019). "All six thermogenes appear to be significantly overexpressed in breast cancer (HSPA1A, HSPA4), gliomas (DNAJB5), ovarian cancers (HSPA4, DNAJB5), pancreatic cancers (HSP90AA1), prostate cancer (HSP90AB1), thymic carcinoma (BAG1, HSP90AA1), and uterine cancers (HSPA4), as compared to normal tissue." (PMID 31814876, 2019). "Furthermore, amplification of HSP90AA1 and/or high-level amplification of HSF1 collectively represents a group of breast cancer samples with up-regulated HSP90AA1 mRNA expression (P = 9.62 × 10-8, n = 481, Mann-Whitney U Test)." (PMID 22510516, 2012). "Thus, HSP90AA1 is considered a potential tumor biomarker, but the utility of measuring plasma HSP90AA1 in breast cancer clinical treatment has not yet been investigated." (PMID 34109171, 2021). "Similarly, a study has found that up-regulated HSP90AA1 mRNA expression indicates poor prognosis of HER2 negative breast cancer patients." (PMID 32662828, 2020). "We observed that 8% of breast cancer samples carried amplifications (both high-level and low-level amplifications, CN ≥3) of HSP90AA1, leading to a higher expression of HSP90AA1, compared with samples without HSP90AA1 amplifications (P = 7.67 × 10-8, n = 481, Mann-Whitney U Test)." (PMID 22510516, 2012). "MCF10A cells exhibited significantly increased expression of HSP90AA1, CARHSP1, HSPA12A and decreased expression of HSPB1, HSPBL2, HSPA6, and HSPA7 (C vs H), while the three breast cancer lines showed no significant 2-fold or greater alterations in the expression of these genes (C’ vs H’)." (PMID 24511912, 2014). "Furthermore, amplification of HSF1 was correlated with higher HSP90AA1 and HSP90AB1 mRNA expression among the breast cancer cells without amplifications of these two genes." (PMID 22510516, 2012).
lung carcinoma (36 papers, 2013 to 2025). "Among the 5-lung cancer associated genes, HSP90AA1 and HIF1A were highly expressed in LUAD and LUSC datasets." (PMID 39113883, 2024). "The data revealed that CDK1 expression levels showed a strong association with the stage of tumor in lung cancer patients as well as HSP90AA1 also showed a strong association with the stage of tumor in lung cancer patients." (PMID 35330393, 2022). "Similarly, such immune infiltration patterns of PSMG4 were recorded in LUAD patients via a TIMER analysis, which neatly supports the strong biological associations between PSMG4 and HSP90AA1 in the context of lung cancer." (PMID 36619227, 2023). "In addition, high expression of HSP90AA1 in lung cancer cells is closely associated with lung cancer progression and treatment response." (PMID 37328788, 2023). "HSP90AB1 and its related homology HSP90AA1 have important potential in the treatment of lung cancer." (PMID 39859536, 2025). "LncRNA KCNQ1OT1 enhances the proliferation of lung cancer cells by upregulating HSP90AA1 and downregulating miR-27b-3p." (PMID 39759512, 2024). "Data revealed a significant upregulation of HSP90AA1 mRNA expression in lung cancer tissues compared with lung normal tissues in all datasets." (PMID 39518920, 2024). "Conversely, Hsp90aa1 is overexpressed in patients with lung cancer, and downregulation of Hsp90aa1 promotes cell apoptosis and inhibits proliferative ability by inhibiting the AKT1/ERK pathway." (PMID 39220589, 2024). "The expression and transcription of HSP90AA1 as well as the activity of the AKT1/ERK pathways were found to be higher in the tissues of lung cancer patients." (PMID 37764733, 2023). "Further, the relationship between the expression of CDK1, HSP90AA1, and tumor stage (pathological stage plot) in lung cancer patients was evaluated using GEPIA." (PMID 35330393, 2022). "HSP90AA1 was consistently up-regulated in lung cancer at both transcriptional and expression levels." (PMID 35095481, 2021). "We then found that AKT1/ERK pathways were also significantly activated in these lung cancer tissues, suggesting a possible contribution of HSP90AA1 to their activation." (PMID 35095481, 2021). "We next knocked down HPS90AA1 in these two cell lines to confirm that the pivotal effect HSP90AA1 in lung cancer." (PMID 35095481, 2021). "For example, previous studies have confirmed that HSP90AA1 is a sensitive biomarker of lung cancer and is valuable in predicting the response of lung cancer patients to surgery or chemotherapy." (PMID 34109171, 2021). "High expression of HSP90AA1, RAC1 and CDKN1A was significantly associated with a lower rate of overall survival in lung cancers." (PMID 32457348, 2020). "An inhibitor of HSP90AA1 was reported to remarkably induce apoptosis and suppress cell proliferation in lung cancer through an ERK/AKT-dependent mechanism and to induce autophagic cell death in osteosarcoma by suppressing AKT/mTOR signaling, highlighting its importance in cancer biology." (PMID 39518920, 2024). "Accordingly, miR-27b-3p suppresses HSP90AA1 expression in lung cancer cells." (PMID 39759512, 2024). "Furthermore, lung cancer patients with high HSP90AA1 levels exhibited lower overall survival than those with low HSP90AA1 expression." (PMID 39518920, 2024). "Direct targeting of HSP90AA1 with daurisoline could destabilize β‐catenin to suppress lung cancer tumorigenesis." (PMID 36822595, 2023). "Interestingly, a missense variant at Y142, which is the hydrogen-bond interaction partner of S164, as well as a CN gain of HSP90AA1 has been reported in PU-H71-resistant lung cancer cells." (PMID 38057328, 2023). "Moreover, the GEPIA tool was used to validate the expression of CDK1 and HSP90AA1 gene expression between lung cancer and control tissue in the LUAD and LUSC cohort from TGCA data." (PMID 35330393, 2022).
lung carcinoma (continued). "Higher levels of both constitutive and stress-inducible HSP90 isoforms in relationship to mitochondrial HSP90 isoform TRAP1 are associated with benign lung diseases such as PM and COPD, whereas a higher level of TRAP1 to HSP90AA1 and HSP90AB1 is associated with lung cancer." (PMID 34692733, 2021). "In both human and mouse lung cancer cell lines, knocking down HSP90AA1 promoted cell apoptosis through the inhibition of the pro-survival effect of AKT1 by decreasing the phosphorylation of itself and its downstream factors of mTOR and BAD, as well as downregulating Mcl1, Bcl-xl, and Survivin." (PMID 35095481, 2021). "However, only HSP90AA1 showed a significant correlation with a shorter overall survival time in lung cancer patients, indicating that it plays an important role in tumor progression." (PMID 35095481, 2021). "As in NSCLC, HSP90AA1 has been well documented to be relevant to lung cancer." (PMID 23762832, 2013). "Additionally, similar immune infiltration patterns between PSMG4 and HSP90AA1 also suggested that PSMG4 may play a certain role in the immune-suppressive TME which is common among lung cancer patients." (PMID 36619227, 2023). "Both CDK1 and HSP90AA1 could be potential therapeutic drug targets in lung cancer treatment." (PMID 35330393, 2022). "AKT1, EGFR, HSP90AA1, SRC, and STAT3 exhibited the highest degree values and were identified as core therapeutic targets for lung cancer." (PMID 41465428, 2025). "Five core protein targets, AKT1, EGFR, HSP90AA1, SRC, and STAT3, were identified as potential mediators of steamed PJR’s anti-lung cancer effects." (PMID 41465428, 2025). "Five core targets, AKT1, EGFR, HSP90AA1, SRC, and STAT3, were identified as key mediators of its anti-lung cancer action, participating in critical signaling pathways including MAPK, PI3K-Akt, and Ras pathways." (PMID 41465428, 2025). "Collectively, these findings suggest that AKT1, EGFR, HSP90AA1, SRC, and STAT3 represent important therapeutic targets for anti-lung cancer intervention." (PMID 41465428, 2025). "The expression levels of the top five lung cancer genes, CTNNB1, STAT3, HIF1A, HSP90AA1, and ERBB2, were determined by comparing them with the LUAD and LUSC datasets using the GEPIA2 web server." (PMID 39113883, 2024). "As HSP90AA1 and CDK2 were important in the cell cycle and pyrimidine metabolism, we had reason to believe that HSP90AA1 and CDK2 have a positive role in lung cancer proliferation." (PMID 35586682, 2022). "It was determined that HSP90AA1 hit downstream genes SRC, PIK3CA, and PIK3R1 to modulate lung cancer progression." (PMID 34833921, 2021). "The higher levels of transcription and expression of HSP90AA1 and the activity of AKT1/ERK pathways were confirmed in lung cancer patient tissues." (PMID 35095481, 2021). "Among them, CTNNB1, ZEB1, CDC42, HSP90AA1, BST2, PCNA, and E2F1 have all been shown to promote lung cancer progression, while SAMHD1, HRAS, and NQO1 serve as tumor suppressor genes." (PMID 28498804, 2017). "Analysis of these shortest path genes indicates that some of these genes, such as ESR1, FDXR, ABCA1, IRS1, HSP90AA1, FOXM1, and IGBP1 are related to lung cancer." (PMID 23762832, 2013). "Specifically, the investigation revealed a connection between the phytochemical constituents and the genes CTNNB1, STAT3, HIF1A, HSP90AA1, and ERBB2, which have established links to lung cancer and play essential roles in the critical cellular pathways involved in disease progression." (PMID 39113883, 2024). "Notably, our findings reaffirm the relevance of lung cancer genes, such as CTNNB1, STAT3, HIF1A, HSP90AA1, and ERBB2, integral to various cellular processes and pivotal in cancer genesis and advancement." (PMID 39113883, 2024). "Of these proteins, HSP90AA1, ITGB1, cytokeratin-8 (KRT8) and receptor for activated C-kinase (RACK1) are identified prognostic markers for overall survival in solid malignancies including lung cancer." (PMID 33777753, 2021).
lung carcinoma (continued). "Furthermore, the higher transcription and expression levels of HSP90AA1 and AKT1/ERK pathways were validated in lung cancer patient tissues." (PMID 35095481, 2021). "Our results, the upregulation expression of HSP90AA1 and CDK2 was related to the inhibited action of NSCLC cells, confirmed the important role of the core targets in lung cancer and may provide new ideas for the related research on guiding the clinical treatment of lung cancer." (PMID 35586682, 2022). "Despite their roles related to lung cancer, the kinases associated with the identified phosphorylation sites matching the CK2 phosphorylation motif, including serine 141 of LIG1, serines 263 and 252 of HSP90AA1 and serines 206, 28 and 34 of NCL, have not been reported." (PMID 28290473, 2017). "The mRNA expression of both genes CDK1 and HSP90AA1 were significantly upregulated in both the datasets, LUAD and LUSC, between lung cancer and non-cancer patients." (PMID 35330393, 2022).
osteosarcoma (26 papers, 2018 to 2026). A usually aggressive malignant bone-forming mesenchymal neoplasm, predominantly affecting adolescents and young adults. "It is worth noting that HSP90AA1 has been associated with cancer drug resistance in multiple studies, including osteosarcoma and ovarian cancer." (PMID 38420434, 2024). "HSP90AA1, functioning as a key promotor of autophagy, is positively associated with the development of osteosarcoma chemoresistance." (PMID 34311656, 2021). "The underlying molecular mechanism of HSP90AA1-mediated autophagy in osteosarcoma chemotherapy also needs to be explored." (PMID 30153855, 2018). "Moreover, we evaluated the association between expression of HSP90AA1 and survival of osteosarcoma cells after anticancer agents treatment." (PMID 30153855, 2018). "HSP90AA1 increases chemotherapy resistance by promoting autophagy and inhibiting apoptosis, and inhibiting HSP90AA1 restores the sensitivity of osteosarcoma cells to chemotherapy in vitro and in vivo." (PMID 41507145, 2026). "In previous studies, HSP90AA1 was able to mediate autophagy in osteosarcoma to promote drug resistance." (PMID 40831924, 2025). "According to the expected core targets of the PPI network that were significantly associated with anti-osteosarcoma effects, the top five target proteins (EGFR, Caspase-3, ESR1, HSP90AA1, and SRC) ranked by degree value were subjected to molecular docking." (PMID 40991530, 2025). "HSP90AA1 inhibited osteosarcoma cell apoptosis by deactivating the JNK/P38 pathway and promoted autophagic protection in response to chemotherapy by blocking the PI3K/AKT/mTOR signaling pathway, thus serving as an important regulator of osteosarcoma survival." (PMID 39430254, 2024). "HSP90AA1 promotes drug resistance in osteosarcoma cells, such as resistance to chemotherapy drugs like doxorubicin, cisplatin, and methotrexate, by inducing autophagy." (PMID 38297292, 2024). "For the development of drug resistance in osteosarcoma, some heat shock protein, such as HSP90AA1, is also related to autophagy." (PMID 38800967, 2024). "HSP90AA1, identified as a cancer enabler, has been shown to be a critical factor in chemoresistance in osteosarcoma by regulating autophagy, with its high expression in BC often linked to poor prognosis." (PMID 38827320, 2024). "As an important regulator of autophagy, HSP90AA1 increases drug resistance by inducing autophagy and inhibiting apoptosis and provides a new therapeutic target for improving the treatment of osteosarcoma." (PMID 35263200, 2022). "HSP90AA1 regulated the tumor development by acting as an effective regulator of autophagy in osteosarcoma." (PMID 36292719, 2022). "AHSA1 is a co-chaperone of HSP90AA1, and a previous study has revealed that it is involved in the proliferation, migration, and invasion processes of osteosarcoma." (PMID 31987030, 2020). "HSP90AA1 is induced by chemotherapeutic reagents, such as doxorubicin, cisplatin, and methotrexate, in osteosarcoma." (PMID 33375363, 2020). "The inhibition of HSP90AA1 restores the sensitivity to chemotherapy in osteosarcoma cells through the reduction of autophagy via the PI3K/AKT/mTOR pathway and the induction of apoptosis via the JNK/P38 pathway." (PMID 33375363, 2020). "We demonstrated that suppression of HSP90AA1 expression significantly increased drug sensitivity of osteosarcoma cells both in vitro and in vivo." (PMID 30153855, 2018). "Our findings showed that knockdown of HSP90AA1 by shRNA promoted cell apoptosis and inhibited osteosarcoma growth both in vivo and in vitro." (PMID 30153855, 2018). "Suppression of HSP90AA1 restored the sensitivity of osteosarcoma cells to chemotherapy both in vivo and in vitro." (PMID 30153855, 2018). "In this study, consistent with the cytoprotective role of autophagy in cancer cells, we demonstrated for the first time that HSP90AA1-mediated autophagy is a significant contributor to drug resistance in osteosarcoma." (PMID 30153855, 2018).